WNT4 (Wnt family member 4)
Diseases named in the same sentence as WNT4 in open-access papers (continued):
Sharing a sentence is not in itself a finding about the gene and the disease.
endometriosis (continued). "The variants with most evidencefor enrichment between the traits, in/near intergenic 7p15.2, KIFAP3and WNT4, were all implicated in WNT signalling andhad consistent—discordant—directions of effect, with endometriosis riskalleles associated with a decreased WHRadjBMI." (PMID 25296917, 2015). "Only rs12037376 (CDC42/WNT4), rs71575922 (SYNE1/ESR1), and rs77294520 (GREB1) associate with leiomyoma after correction for the number of tests (P < 0.05/19 = 2.6 × 10−3), with all three variants showing the same direction of effect for endometriosis and leiomyoma (logistic regression)." (PMID 30194396, 2018). "With all the evidence from the literature, WNT4, through its prominent role in development of the female reproductive tract, ovarian follicle development, and steroidogenesis, might play a critical role in development of endometriosis." (PMID 22924156, 2012). "Moreover, WNT4 is expressed in normal peritoneum, suggesting that endometriosis may arise through metaplasia using developmental pathways involved in the development of the female genital tract." (PMID 22924156, 2012). "There were three stromal cellular contexts in which the expressions of RSPO3, WNT4, and ESR1 were significantly different depending on endometriosis status." (PMID 41377979, 2025). "Genes shared between endometriosis, uterine fibroids, ovarian and endometrial cancer, asthma and migraine (CDC42, WNT4, SMAD3, SKAP1) were enriched in cell adhesion pathways." (PMID 37159502, 2023). "At 1p36.12, there is an important locus involved in endometriosis encompassing LINC00339, CDC42 and WNT4 in a LD block of ~130 kb." (PMID 34298916, 2021). "An independent set of 305 laparoscopically proven endometriosis patients and 2710 controls confirmed WNT4, CDKN2BAS, and FN1 as the first identified common loci for endometriosis." (PMID 25722978, 2015). "During the proliferative phase, all three were upregulated in nondecidualized stromal cells from donors with endometriosis; in the early secretory phase, WNT4 switched to being downregulated, and in the mid secretory phase, both WNT4 and RSPO3 were diminished." (PMID 41377979, 2025). "Though these considerations support WNT4 as a candidate predisposition gene at this locus, the near-by CDC42 has been shown to play a role in uterine pathology, in particular endometriosis, and should not be overlooked in further work." (PMID 30226466, 2018). "In addition to 7p15.2, weidentify four more variants with statistically significant evidence of involvement inboth endometriosis and WHRadjBMI (in/near KIFAP3,CAB39L, WNT4, GRB14); two ofthese, KIFAP3 and CAB39L, are novel associationsfor both traits." (PMID 25296917, 2015). "Similarly, genes shared between endometriosis, uterine fibroids, ovarian cancer, migraine and depression (RHOA, FOXP1, ESR1, WNT4, GREB1, FSHB), and endometriosis, migraine and asthma (IGF1, SMAD3, MFHAS1), were enriched in hormone receptor signalling and inflammation pathways, respectively." (PMID 37159502, 2023). "Genome-wide association studies on endometriosis have demonstrated an association between susceptibility to the disease and markers located in or near the WNT ligand WNT4 gene encoding for a noncanonical key player in the development of the female reproductive tract." (PMID 34445738, 2021). "This showed that there is an overlap between endometriosis and fat distribution evaluated for instance, by the waist-to-hip ratio adjusted for BMI, and allowed the identification of novel loci near KIFAP3 and CAB39L, and shared genetic basis for WNT4, GRB14 and the intergenic region 7p15.2." (PMID 34298916, 2021). "The strongest burden statistic was on chromosome 1p36 (the region encompassing ZBTB40, WNT4 and CDC42), with two types of ovarian cancer (clear cell carcinoma and high-grade serous carcinoma, while epidemiologically, endometriosis does not constitute a risk factor for this last type of cancer)." (PMID 34298916, 2021).
breast carcinoma (32 papers, 2006 to 2025). "Wnt ligand WNT4 is critical in female reproductive tissue development, with WNT4 dysregulation linked to related pathologies including breast cancer (invasive lobular carcinoma, ILC) and gynecologic cancers." (PMID 38112643, 2024). "Decreased progenitor cell potential during parity (and subsequent parity-induced breast cancer protection) is linked to downregulation of Wnt4, but progenitor cell proliferation is rescued by Wnt4 induction or exogenous WNT4." (PMID 27650553, 2016). "Furthermore, HB‐EGF, COX‐2, and Wnt4 as well as Bmp2 have been shown to be risk factors for sex hormone‐dependent diseases, such as prostatic hyperplasia, breast cancer, and ovarian cancer." (PMID 28588064, 2017). "Taken together, these observations suggest that ER+ ILC cells and tumors have a distinct metabolic phenotype compared with other breast cancers, which our work links directly to WNT4-dependent signaling activity." (PMID 38112643, 2024). "In contrast, high WNT4 gene expression has been reported in human breast cancer tissue, thymoma tissue, and colorectal cancer." (PMID 37835474, 2023). "Research has shown that WNT4 is highly expressed in the human breast cancer tissue, thymoma tissue, and colorectal cancer (CRC) tissue." (PMID 34642299, 2021). "So far as the action mechanism is concerned, estrogen and progesterone are the upstream agitators of WNT4 expression in mammary cancer." (PMID 34642299, 2021). "In a previous study, it has been reported that WNT4 promoted the proliferation of breast cancer stem cells, and promoted progression of gastric cancer, which suggested a pro-carcinogenic role of WNT4." (PMID 33222684, 2020). "Autocrine GH stimulates WNT4 expression in breast cancer cells, which, in turn, increases mesenchymal markers vimentin, MMP2, and MMP7, while inducing cell migration and suppressing apoptosis." (PMID 31939481, 2019). "Further, both GH and WNT4 are upregulated in human mammary carcinoma and tumor xenografts expressing GH." (PMID 31939481, 2019). "We collected benign breast tissue of 125 women who had been stratified according to age at first pregnancy and the occurrence of subsequent breast cancer, and performed immunohistochemistry for PR, Wnt4 and the Wnt-target Versican." (PMID 28423605, 2017). "Despite the small sample size, we demonstrated a relationship between a higher expression of certain components of the Wnt pathway, such as PR, Wnt4 and Versican, and the occurrence of subsequent breast cancer." (PMID 28423605, 2017). "WNT ligands WNT1, WNT10a and WNT4 were expressed at higher levels in normal AR cells compared to monolayer cells, however in the breast cancer cell lines, their expression was lower in the AR cells compared to monolayer cells." (PMID 23861811, 2013). "Little is known about the role of WNT10A in breast cancer but Wnt4 is essential for normal progesterone induced mammary gland development." (PMID 23861811, 2013). "WNT4 is important for the development of the female reproductive system and breast cancer." (PMID 40585091, 2025). "Research has demonstrated that WNT4 could promote breast cancer stem cell proliferation and the progression of gastric cancer." (PMID 34642299, 2021). "In breast cancer, co-expression of Wnt ligands, including Wnt3, Wnt4, Wnt5a, and Wnt7a, leads to the activation of Wnt pathway, while in colorectal cancer, mutation or loss function of the APC gene or protein is more likely to be the reason for Wnt pathway activation." (PMID 29986466, 2018). "We also analyzed 7 breast cancer cases (3 from Group 2/nulliparous women, 2 from Group 3/early pregnancy and 2 from Group 5/late pregnancy) with immunohistochemistry against PR, Versican, Wnt4, CD15 and β-Catenin." (PMID 28423605, 2017). "Notably, NEAT1 is found overexpressed in BRCA1-deficient breast cancer and promotes self-renewal abilities in breast cancer cells through epigenetically suppressing miR-129-5p, which targets to Wnt4." (PMID 28615056, 2017).
breast carcinoma (continued). "In the present study, we performed immunohistochemistry for PR, Wnt4, Versican, β-catenin and CK-15 on breast tissue from different subpopulations of women, stratified according to age at first pregnancy and occurrence of breast cancer." (PMID 28423605, 2017). "Wnt4 regulates the proliferation of breast cancer stem cells in response to progesterone." (PMID 26918831, 2016). "To determine whether WNT4 is necessary for breast cancer cell proliferation, we used siRNA to knock down WNT4 expression in breast cancer cell lines (BCCLs)." (PMID 27650553, 2016). "Indeed, the elevated expression of WNT4 is frequently observed in many breast cancer patients which implies that it's aberrant expression leads to abnormal cell proliferation and breast cancer in women." (PMID 23843947, 2013). "Furthermore, our data suggests that normal breast cancer stem cells express different WNT ligands (WNT4 and WNT10) than BCSCs when compared to their monolayer populations." (PMID 23861811, 2013). "Similarly, the effects of antiestrogen fulvestrant were highly correlated in parental versus W4OE, as WNT4 may be insufficient to overcome complete ER inhibition in ER-dependent breast cancer cells." (PMID 38112643, 2024). "Using qRT-PCR, we validated this proposed downregulation with the experimental detection of decreases in GLI2 and WNT4 mRNA levels following 9 days of 15 μM RSV treatment in MCF-7 and MCF10CA1a breast cancer cells." (PMID 38474826, 2024). "E2F1 and E2F4 induce whereas pRb/RBL2 reduce WNT ligand expression (e.g. WNT7A, WNT7B, WNT10A, WNT4) thereby regulating self-renewal, chemoresistance and invasiveness of CSCs in both PDAC and breast cancer, and fibroblast proliferation." (PMID 38678032, 2024). "Perhaps consistent with this role of WNT4 in migration/invasion, both OvCa and ILC metastasize to the abdomen/peritoneal cavity, ILC being unique among breast cancers in this regard." (PMID 33053661, 2020). "Proliferation of non-stem breast cancer cells was also affected since depletion of WNT7B/WNT4/WNT3A reduced cell cycle progression while addition of purified WNT7B and WNT4/WNT3A to media had the opposite effect." (PMID 38678032, 2024). "In breast cancer cells, there is overexpression of WNT3A, WNT4, WNT6, WNT8B, WNT9A and WNT10B." (PMID 35453754, 2022). "In breast cancer cells and in solid autocrine human growth hormone (hGH) tumours, both WNT4 and its receptor FZD6 were upregulated indicating that WNT4 is a strong Wnt ligand candidate to activate FZD6." (PMID 35237656, 2022). "In contrast, WNT4 was not differentially expressed upon ROR2 overexpression in the investigated breast cancer cell lines." (PMID 34911552, 2021). "In accordance to correspondent mouse studies, we found significantly more PR and Wnt4 positive epithelial cells in nulliparous women with subsequent invasive breast cancer compared to women with early pregnancy and no subsequent breast cancer." (PMID 28423605, 2017). "Within the group of women without subsequent breast cancer, we detected a significantly higher number of Wnt4-positive cells in the group of nulliparous women (Group 1) compared to the group of women with early pregnancy (Group 4, p = 0.0449)." (PMID 28423605, 2017). "To test this hypothesis, we assessed regulation and expression of WNT4, WNT4 signaling, and WNT4-mediated phenotypes in ILC- and IDC-derived breast cancer cell lines." (PMID 27650553, 2016). "β-Catenin-independent WNT4 signaling has not been extensively characterized in the breast or in breast cancer." (PMID 27650553, 2016). "WNT3A, WNT4, WNT6, WNT8B, WNT9A, and WNT10B all are overexpressed in many breast cancer cell lines." (PMID 16933995, 2006). "WNT1, WNT4, and the Wnt pathway components AXIN2 and LEF1 are upregulated in breast cancers." (PMID 16933995, 2006). "CDK5 may be a potential link between WNT4 and p70-S6K, as CDK5 has been linked to non-canonical Wnt signaling as well as mitochondrial function in breast cancer cells." (PMID 33053661, 2020).
breast carcinoma (continued). "Additionally, a significantly higher number of Wnt4-positive cells in nulliparous with subsequent cancer group (Group 2) when compared to the late pregnancy group without subsequent breast cancer was found (Group 6, p = 0.0368, Mann-Whitney U test)." (PMID 28423605, 2017). "Interestingly, there was also a significantly higher number of Wnt4-positive cells in the nulliparous group with subsequent breast cancer (Group 2) when compared to the early pregnancy group without breast cancer (Group 4, p = 0.0229, Mann-Whitney U test)." (PMID 28423605, 2017). "The discovery of the BRCA1/NEAT1/miR-129-5p/WNT4 axis and the pivotal roles of WNT4 in WNT signaling activation as well as in the enhancement of BCSC generation suggest that WNT signaling is a potential therapeutic target for breast cancer with alterations in this signaling axis." (PMID 27556296, 2016). "Based on the role of TGFB1 (inhibition of proliferation) and WNT4 (induction of proliferation) in non-cancer tissues, these influences could result in less proliferation of breast epithelium in women without breast cancer." (PMID 34921608, 2022). "Furthermore, the number of Wnt4 positive cells in women with either early or late pregnancy was significantly lower when compared to that in nulliparous women, independent of subsequent breast cancer occurrence." (PMID 28423605, 2017).
hyperandrogenism (18 papers, 2007 to 2026). Excessive secretion of androgens from the adrenal glands or gonads. "Monoallelic WNT4 variants cause Mullerian duct failure and hyperandrogenism, while biallelic WNT4 variants cause SERKAL syndrome (46,XX DSD, dysgenetic kidneys, adrenals, and lungs)." (PMID 38812815, 2024). "Detailed functional analysis of three WNT4 mutations in 46,XX individuals with Müllerian duct abnormalities and hyperandrogenism suggested that WNT4 is involved in ovarian development through repression of androgen biosynthesis." (PMID 35721511, 2022). "Since WNT4 is also necessary to prevent formation of Leydig cells in women, patients with mutated WNT4 also present with clinical hyperandrogenism, rendering it a slightly different clinical entity." (PMID 35394036, 2022). "Inactivating germline mutations in WNT4 cause mullerian aplasia and hyperandrogenism (MIM 158330) and are responsible for the autosomal recessive SERKAL syndrome (Sex Reversal and Kidney, Adrenal, and Lung dysgenesis; MIM 611812)." (PMID 25990418, 2015). "MRKH syndrome does not present with clearly identifiable genetic causes except in a Wnt4-associated atypical form with clinical and biological signs of hyperandrogenism." (PMID 24641817, 2014). "Function-disrupting mutations of WNT4, a gene critical for female sex determination and organogenesis, are associated with Müllerian aplasia, ovarian follicle depletion, and hyperandrogenism in women." (PMID 24465770, 2014). "As only 28.6% of the 60.8% of MRKH women with hyperandrogenemia in our study had acne as a clinical sign of androgen excess, a mutation within the WNT4 gene cannot be expected in the majority of our hyperandrogenemic patients." (PMID 24641817, 2014). "Evidence of hyperandrogenism in women presenting with normal female phenotype should then initially direct the clinicians to suspect WNT4 as a cause." (PMID 17359527, 2007). "In addition, De novo or rare WNT4 genes mutations were only identified in MRKH patients with hyperandrogenism." (PMID 37789575, 2023). "However, no monogenetic factor of MRKH has been identified yet in addition to WNT4 mutations observed in patients with hyperandrogenism, which suggests the need of more researches in this field." (PMID 37789575, 2023). "For this reason, when MRKH syndrome is combined with signs of hyperandrogenism, heterozygous variants of the WNT4 gene may be considered." (PMID 35883945, 2022). "The WNT4 gene mutations were proved to cause MRKHS in some patients with hyperandrogenism." (PMID 34768925, 2021). "Finally, mutations in WNT4 have been reported in females with Müllerian aplasia and hyperandrogenism, although it is thought to be an entity that differs from MRKH syndrome." (PMID 28003020, 2016). "The dominant-negative mutation of WNT4 may then produce two distinct effects, hyperandrogenism and uterine aplasia." (PMID 17359527, 2007). "So far, three causative WNT4 mutations (p.R83C, p.L12P, p.A233T) were identified in adolescents with MRKHS and hyperandrogenism." (PMID 34768925, 2021). "The only known MRKH-associated mutations are located within the WNT4 gene and lead to an atypical form of MRKH syndrome associated with clinical and biochemical hyperandrogenism." (PMID 24641817, 2014). "Mutations in WNT4 have been found in patients with MRKH and hyperandrogenism." (PMID 33763415, 2021). "The WNT4 case reports did not comprehensively study other genomic aberrations these patients might carry, so it is unknown whether mutant WNT4 is the only contributor to the MRKH/hyperandrogenism phenotype." (PMID 34160006, 2021). "However, in WNT4, which is associated with a distinct clinical entity of MRKH syndrome and signs of hyperandrogenism, and in its family member WNT9B, causative mutations have also been detected." (PMID 29527097, 2018).
hyperandrogenism (continued). "Thus, according to one study, the absence of a WNT4 mutation in four adolescent girls with MRKH syndrome and clinical and biochemical hyperandrogenism strongly suggests the potential involvement of other constituents of the Wnt4/β-catenin signaling pathway." (PMID 24641817, 2014). "The first mutation found and proved causative of MRKHS concomitant with hyperandrogenism without clinical signs of virilization (OMIM 158330) was the Q226G missense mutation of the WNT4 protein, due to a heterozygous substitution of guanine for adenine in exon 5 of the WNT4 gene." (PMID 34768925, 2021). "Moreover, some patients with MRKH and hyperandrogenism lacked mutations in WNT4, suggesting that other components of the WNT pathway might be altered or that other pathways might be responsible." (PMID 34160006, 2021). "Differential diagnosis includes isolated vaginal atresia, androgen insensitivity syndrome caused by mutations of the androgen receptor gene (AR) in XY individuals and WNT4 defects characterised by MRKH and hyperandrogenism." (PMID 29527097, 2018). "Clinically, WNT4 defects may mimic MRKH syndrome, but evidence of hyperandrogenism in an otherwise phenotypically female patient should prompt suspicion of WNT4 involvement." (PMID 41515635, 2026). "For instance, some patients with MRKH associated with hyperandrogenism bear mutations in WNT4, although mutational analysis of MRKH women without hyperandrogenism did not identify disruptions in this gene." (PMID 34160006, 2021). "However, the individual role of this gene is not well delimited as WNT4 mutations in MRKH patients not exhibiting hyperandrogenism could not be found and not all MRKH patients with hyperandrogenism have WNT4 mutations." (PMID 33763415, 2021).